KDM6A (lysine demethylase 6A)
Diseases named in the same sentence as KDM6A in open-access papers (continued):
Sharing a sentence is not in itself a finding about the gene and the disease.
Sepsis (3 papers, 2022 to 2023). Sepsis is defined as life-threatening organ dysfunction caused by a dysregulated host response to infection. "We reported that chemical inhibition of KDM6A by GSK-J4 significantly reduces Hotairm1 transcripts in late sepsis Gr1+CD11b+ cells." (PMID 39665047, 2023). "During late sepsis, the histone demethylase KDM6A catalyzes the removal of H3K27me3, leading to PU.1 binding and activation of Hotairm1 transcription." (PMID 39665047, 2023). "During late sepsis, histone lysine demethylase KDM6A removes H3K27me3, increasing the transcription activation marks H3K4me3 and subsequently activating its transcription by PU.1." (PMID 39665047, 2023). "We conclude that KDM6A plays an important role in reducing repressor mediator H3K27me3 on the Hotairm1 promoter, thereby increasing Hotairm1 during sepsis." (PMID 35185915, 2022). "In this study, we extended our mechanistic and translational research by identifying KDM6A as a promoter of the epigenetic exchanges that induce Hotairm1 transcription in MDSCs during sepsis." (PMID 35185915, 2022). "Using the polymicrobial mouse model of sepsis, we discovered an epigenetic signature directed by the histone lysine demethylase, KDM6A, in MDSCs from mice with later sepsis." (PMID 35185915, 2022). "KDM6A protein binds to Hotairm1 proximal promoter following sepsis initiation, and its binding peaks in later sepsis MDSCs." (PMID 35185915, 2022). "Mechanistically, KDM6A demethylates the transcription repressive H3K27me3 mark that is deposited on the Hotairm1 promoter as sepsis progresses to the later, protracted state." (PMID 35185915, 2022). "To support translation to human sepsis, we demonstrate that inhibiting H3K27me3 demethylation by KDM6A ex vivo in MDSCs from patients with protracted sepsis decreases Hotairm1 transcription." (PMID 35185915, 2022). "Using a mouse model that simulates the immunobiology of sepsis, we find that histone demethylase KDM6A promotes Hotairm1 transcription by demethylating transcription repression H3K27me3 histone mark." (PMID 35185915, 2022). "This is supported by the finding that KDM6A/B inhibition with GSK-J4 promoted survival in mice with E. coli-induced sepsis by dampening the inflammatory response, including the production of the pro-inflammatory cytokines IL-1β, TNFα, IL-6 and CCL2, and directly suppressing the growth of E. coli." (PMID 35915507, 2022). "The H3K27 demethylases KDM6A and KDM6B have been shown to play a role in the activation of the fatal inflammatory response in E. coli-induced sepsis." (PMID 35915507, 2022). "Here, we used KDM6A potent and specific inhibitor GSK-J4 to modulate Hotairm1 RNA transcription in sepsis MDSCs." (PMID 35185915, 2022). "Here, we found that KDM6A specific inhibitor GSK-J4 supports an exchange between H3K27me3 and H3K4me3 at Hotairm1 promoter in mouse and human MDSCs, thereby mediating the effect of other bioactive mediators of sepsis immunosuppression (e.g., IL-10)." (PMID 35185915, 2022).
Stroke (3 papers, 2021 to 2024). Sudden impairment of blood flow to a part of the brain due to occlusion or rupture of an artery to the brain. "All these data suggest that Kdm6a and Kdm5c signaling are pro-inflammatory after stroke in the aged." (PMID 39399684, 2024). "Our prior research has suggested that the X escapee genes Kdm6a and Kdm5c are involved in microglial activation after stroke in aged mice." (PMID 39399684, 2024). "We also examined the effect of Kdm5c’s signaling on stroke outcomes, and found the similar results as that of Kdm6a." (PMID 39399684, 2024). "We also found that the ratio of KDM6A+Iba-1+ cells in female stroke brains was significantly higher than that of males." (PMID 33712031, 2021). "The present study focused on two X chromosome escapee genes, Kdm6a and Kdm5c, and investigated their epigenetic modulation of IRF5/IRF4 via demethylation of H3K27Me3/H3K4Me3 in aged microglia after stroke." (PMID 39399684, 2024). "We hypothesized that Kdm6a/5c regulate IRF5/4 expression through epigenetic modification of histones, mediate microglial activation/neuroinflammation after stroke, and impact outcomes." (PMID 39399684, 2024). "However, the mechanism by which Kdm6a/Kdm5c modulates IRF5/4 gene signaling and neuroinflammation after stroke is still elusive." (PMID 39399684, 2024).
acute promyelocytic leukemia (2 papers, 2019 to 2021). An aggressive form of acute myeloid leukemia (AML), characterized by arrest of leukocyte differentiation at the promyelocyte stage, due to a specific chromosomal translocation t(15;17) in myeloid cells. "We previously identified recurrent loss-of-function somatic mutations and deletions of Kdm6a in a mouse model of acute promyelocytic leukemia." (PMID 34780480, 2021).
amyloid (2 papers, 2023). "However, the role of Kdm6a and sex-specific histone modifications have not been explored in microglia with aging or in response to amyloid pathology." (PMID 36945656, 2023).
Anxiety (2 papers, 2017 to 2021). Intense feelings of nervousness, tension, or panic often arise in response to interpersonal stresses. "Mouse with Kdm6a knockout exhibits slightly different phenotype between male and female: the female Kdm6a-knockout mouse shows higher mortality rate and exhibited anxiety-like behaviors than male." (PMID 34568320, 2021).
aortic aneurysm (2 papers, 2016 to 2018). A ruptured aneurysm located in the wall of the proximal portion of the descending aorta proceeding from the arch of the aorta. "Additionally, the implementation of genetic testing to identify genes associated with malformations (ZFYVE9, TIMP1, PRKX, KDM6A) can lead to a higher detection rate of aortic aneurysm formation, congenital urinary malformations and other anomalies." (PMID 29537378, 2018). "We point to candidate genes of comorbidity in TS e.g. congenital urinary malformations (PRKX), premature ovarian failure (KDM6A) and aortic aneurysm (ZFYVE9 and TIMP1)." (PMID 27687697, 2016). "We describe novel candidate genes that could be involved in comorbidity in TS and explain congenital urinary malformations (PRKX), premature ovarian failure (KDM6A), and aortic aneurysm formation (ZFYVE9 and TIMP1)." (PMID 27687697, 2016).
chronic kidney disease (2 papers, 2022 to 2023). Impairment of the renal function secondary to chronic kidney damage persisting for three or more months. "Cognizant that advances in chronic kidney disease (CKD) therapeutics have shifted the spotlight towards damage of kidney tubules as being the primary force in CKD progression, we explored the expression and actions of KDM6A in tubule epithelial cells." (PMID 37655466, 2023).
cognitive decline (2 papers, 2021 to 2025). "The same study found that a genetic variant in KDM6A was associated with a lesser degree of cognitive decline in humans." (PMID 34281203, 2021).
craniosynostosis (2 papers, 2020 to 2022). Craniosynostosis is defined as the premature fusion of one or more cranial sutures leading to secondary distortion of skull shape resulting in skull deformities with a variable presentation. "In this study, we demonstrate for the first time that the histone demethylases, Kdm6a, and Kdm6b have the potential to be used as novel therapeutic targets for the prevention of craniosynostosis in an SCS mouse model, where the Twist-1 gene is mutated." (PMID 33298158, 2020). "Pharmacological targeting of Kdm6a/b activity can alleviate craniosynostosis in Saethre-Chotzen syndrome." (PMID 33298158, 2020). "Collectively, our findings provided evidence that Kdm6a and Kdm6b are putative targets in treating craniosynostosis in Twist-1del/+ mutant mice and confirmed previous studies that deregulated epigenetic patterns play significant roles in the development of craniosynostosis." (PMID 33298158, 2020). "The inhibition of Kdm6a and Kdm6b activity by GSK-J4 could be used as a potential non-invasive therapeutic strategy for preventing craniosynostosis in children with SCS." (PMID 33298158, 2020).
endometrial carcinoma (2 papers, 2023 to 2025). A malignant tumor arising from the epithelium that lines the cavity of the uterine body. "Although patient 18 (KDM6A variant) developed endometrial cancer (subtype not provided) at a young age (≤ 31 years), approximately ≤5% of endometrial cancers are reported to occur in women younger than 40 years." (PMID 35856126, 2023).
epilepsy (2 papers, 2022 to 2025). A brain disorder characterized by episodes of abnormally increased neuronal discharge resulting in transient episodes of sensory or motor neurological dysfunction, or psychic dysfunction. "In particular, we underline the predominantly neurological phenotype of KDM6A mutations, in which epilepsy, seizures, or EEG anomalies seem much more frequent." (PMID 34232366, 2022). "Interestingly, both patients (2/2) with KDM6A mutations showed sporadic pointed waves and epilepsy with paroxysm." (PMID 34232366, 2022).
Ewing sarcoma (2 papers, 2022 to 2025). A small round cell tumor that lacks morphologic, immunohistochemical, and electron microscopic evidence of neuroectodermal differentiation. "Ewing sarcoma ranks 12th among cancer malignancies with the highest mRNA expression levels of KDM6A." (PMID 41085408, 2025). "The decrease in gene expression of EWSR1::FLI1-KDM6A targets identified by ChIP-seq was confirmed in a second Ewing sarcoma cell line, TC-71, upon KDM6A KO." (PMID 41085408, 2025). "Among the Ewing sarcoma cell lines, the expression of KDM6A was similar in cell lines containing EWSR1::ERG compared with those containing EWSR1::FLI1, whereas KDM6B showed higher levels in those with EWSR1::FLI1." (PMID 41085408, 2025). "Moreover, when we treated Ewing sarcoma cells with the KDM6A/KDM6B demethylase inhibitor GSK-J4, we found that the expression of EWSR1::FLI1-activated targets decreased strongly in those targets containing only KDM6B, suggesting that GSK-J4 phenocopies expression changes induced by KDM6B deletion." (PMID 41085408, 2025). "KDM6A had a demethylase-independent role in recruiting BRG1 at EWSR1::FLI1-primed enhancers containing single GGAA motifs, which was critical for Ewing sarcoma tumor growth." (PMID 41085408, 2025). "Although KDM6A expression was similar across tumor types, KDM6B was expressed at higher levels in Ewing sarcoma cell lines than in other sarcomas." (PMID 41085408, 2025). "The intersection obtained in A-673 was validated in a second Ewing sarcoma cell line, TC-71, in which we found 1,163 common peaks between EWSR1::FLI1 and KDM6A/KDM6B (P value < 0.05; FDR <10−5 in all cases)." (PMID 41085408, 2025). "Analysis of KDM6A and KDM6B by IHC in 43 Ewing sarcoma primary tumor specimens from newly diagnosed patients at our institution revealed that both demethylases were highly expressed by semiquantitative H-score analysis." (PMID 41085408, 2025). "In this study, we shed light on the dynamics of H3K27me3 removal by KDM6A and KDM6B demethylases within the context of Ewing sarcoma." (PMID 41085408, 2025). "To gain insight into the role of both demethylases on the EWSR1::FLI1 transactivation activity, we knocked down KDM6A and KDM6B in two Ewing sarcoma cell lines, A-673 and TC-71, using a doxycycline-inducible system." (PMID 41085408, 2025). "IHC analysis of tumors confirmed the expression of the Ewing sarcoma marker CD99 and significantly lower expression of KDM6A and the proliferation marker Ki-67 in sgKDM6A-derived tumors." (PMID 41085408, 2025). "Taken together, gene expression data and IHC studies indicate that KDM6A and KDM6B are highly expressed in Ewing sarcoma cell lines and primary tumor samples." (PMID 41085408, 2025). "The differential location and partnership identified for each of the KDM6 demethylases in Ewing sarcoma suggest that KDM6B specifies EWSR1::FLI1 for the most active regions and KDM6A signals for a specific set of enhancers that commit to neural lineage." (PMID 41085408, 2025). "To shed light on whether KDM6A and KDM6B demethylases are involved in H3K27me3 to H3K27ac switches in enhancers regulated by EWSR1::FLI1, we carried out ChIP-seq for KDM6A, KDM6B, and EWSR1::FLI1 in the Ewing sarcoma cell line A-673." (PMID 41085408, 2025). "KDM6A and KDM6B mediate critical mechanisms behind EWSR1::FLI1 transcriptional activation program involving demethylase-independent and dependent functions, respectively, supporting the development of therapeutic strategies targeting these demethylases in Ewing sarcoma." (PMID 41085408, 2025). "Although, in hpMSCs, overexpression of EWSR1::FLI1 remodels the chromatin landscape by redistributing H3K27me3, in Ewing sarcoma cell lines, depletion of KDM6B—but not KDM6A—exerts its main effects partly by restoring H3K27me3 levels at enhancers." (PMID 41085408, 2025).
goblet cell adenocarcinomas (2 papers, 2023). "Defects in the functioning of the KDM6A gene are present in Kabuki syndromes 1 and 2, and mutations in this gene are reported in a few cases of appendiceal goblet cell adenocarcinomas." (PMID 37509254, 2023). "KDM6A and KMT2D mutations have been reported in the appendiceal goblet cell carcinoid, mixed goblet cell carcinoid–adenocarcinoma, and some appendiceal mucinous adenocarcinomas and adenocarcinomas." (PMID 37566041, 2023). "Most of these mutations were also identified in other studies; for example, mutations in KDM6A, KMT2D, SMARCA4, and ARID1A have been previously reported not only in appendiceal adenocarcinomas but also in appendiceal goblet cell carcinomas." (PMID 37566041, 2023).
immunodeficiencies (2 papers, 2020 to 2023). "Similar results were observed for four other genes on chromosome X, KDM6A, which is somatically involved in BL39, and BTK, SH2D1A40, and XIAP41, which are indirectly linked with BL risk via X-linked immunodeficiencies related to EBV." (PMID 38057307, 2023).
ischemic stroke (2 papers, 2024 to 2025). A stroke disorder caused by obstruction of blood flow to the brain, due to thrombotic (local blood clot formation) or embolic (due to a blood clot or other material traveling from another site) event. "It is worthy to note that histone demethylase KDM6A exhibited lower level in aged males compared to the age-matched females after ischemic stroke, which was consistently observed in either human whole blood or mice T cells." (PMID 40191607, 2025). "Functioning as a histone H3 demethylase, Kdm6a has been linked to enhanced activation of female CD4 + T cell in EAE, as well as female microglial activation in ischemic stroke." (PMID 38486287, 2024). "Therefore, we explored whether KDM5C, KDM6A, or EIF2S3 displayed age-dependent expression changes in males and females and whether such age-dependent expression changes could be altered by ischemic stroke." (PMID 40191607, 2025).
learning disabilities (2 papers, 2022 to 2023). "Examples are the leukaemia-protecting histone demethylase KDM6A, FMR1, a gene linked to Fragile-X and learning disability, and the Duchenne muscular dystrophy gene DMD." (PMID 36802379, 2023).
lung adenocarcinoma (2 papers, 2021 to 2025). A carcinoma that arises from the lung and is characterized by the presence of malignant glandular epithelial cells. "We again observed significantly higher of KDM6A-pSer829 levels in tumors than in adjacent tissues in a cohort of Lung Squamous cancer, Lung Adenocarcinoma, and Liver Hepatocyte cancer patients." (PMID 41184251, 2025).
metastatic disease (2 papers, 2019 to 2021). "The primary and metastatic tumours demonstrated the somatic mutations FBXW7 Q242H, FBXW7 S582L as well as KDM6A S763I and PIK3C2B Q877_W878K, suggesting the possibility of bi-allelic FBXW7 loss resulting in a high level of MYC protein expression, which was documented in the metastatic tumour." (PMID 33311588, 2021). "In addition to CTNNB1‐activating mutations, we found inactivating mutations of epigenetic regulators (KDM6A, TET1, BAP1) associated with metastatic disease." (PMID 30306561, 2019). "In our cohort of SPNs, we found that a lack of or reduced expression of both KDM6A and BAP1 is enriched in metastatic cases, suggesting that their function is a barrier to the development of metastatic disease at least in a subset of SPNs." (PMID 30306561, 2019).
ovarian carcinoma (2 papers, 2023 to 2025). A malignant neoplasm originating from the surface ovarian epithelium. "Using the Igrov-1 model of PARPi-resistant ovarian cancer, we compared the PARPi sensitizing effect of methylstat with commercially available DNA histone demethylases, including JMJD-specific inhibitors GSK-J1 (JMJD3, KDM6A) and PFI-90 (JMJD1B) and GSK-LSD1, a non-JMJD demethylase LSD1 inhibitor." (PMID 39915607, 2025).
type 1 diabetes (2 papers, 2021 to 2022). "Lower E-cadherin expression is related to a higher level of KDM6A, while E-cadherin is promoted upon treatment with the KDM6A inhibitor GSK-J4 in both high glucose- (HG-) induced HK2 cells and the kidneys from streptozotocin- (STZ-) induced type 1 diabetic mice." (PMID 34257820, 2021).
adenoid cystic carcinoma (1 paper, 2015). A malignant tumor arising from the epithelial cells. "The most common genetic aberrations among patients with adenoid cystic carcinoma (N = 49) were NOTCH1/2 (26.5% [13/49]) (mainly NOTCH1 (24.5% [12/49]) and KDM6A (26.5% [13/49])." (PMID 26247885, 2015).
adenovirus infection (1 paper, 2021). "To confirm the role of KDM6A in the proliferation of T24 and 5637 cells, we performed a transient adenovirus infection." (PMID 34006303, 2021).
Arthritis (1 paper, 2022). Inflammation of a joint. "As an example, lncRNA H19 promotes M1 macrophage polarization and aggravates arthritis by upregulating KDM6A expression, which contradicts the role of H19 in promoting M2 polarization through the H19-miR let-7a/c-Myc axis in IPF." (PMID 36685535, 2022). "Additionally, H19 overexpression promoted M1 macrophage polarization along with increased expression of M1 macrophage-related factors and aggravated arthritis in mice by upregulating KDM6A expression." (PMID 36685535, 2022).
atherosclerosis (1 paper, 2026). A disease characterized by the build-up of fatty material and calcium deposition in the arterial wall resulting in partial or complete occlusion of the arterial lumen. "Consistently, female mice lacking KDM6A specifically in hepatocytes develops pro-atherogenic blood lipoprotein profiles and increased atherosclerosis under genetic and dietary stress, whereas males are largely unaffected." (PMID 41872164, 2026).
autism (1 paper, 2022). Persistent deficits in social interaction and communication and interaction as well as a markedly restricted repertoire of activity and interest as well as repetitive patterns of behavior. "In alignment with this hypothesis, mutations in both H3K27 demethylases, KDM6A and KDM6B, have been associated with autism, linking defects in a H3K27me3-antagonizing mechanism with autism etiology." (PMID 36417527, 2022).
colon adenocarcinoma (1 paper, 2021). "Our results showed a lower KDM6A expression, lower KDM6A exon expression, and higher KDM6A DNA methylation than their corresponding normal tissues in colon adenocarcinoma (COAD)." (PMID 33174323, 2021).
colorectal adenocarcinoma (1 paper, 2022). The most common type of colorectal carcinoma. "UTX (also known as KDM6A) as a highly mutated gene encoding histone H3K27 demethylase has been reported in several cancer cell lines including colorectal adenocarcinoma and pancreatic adenocarcinoma." (PMID 35965507, 2022).
congenital heart disease (1 paper, 2022). A heart disease that is present at birth. "Mutations in histone modifiers KMT2D (histone-lysine N-methyltransferase 2D) and KDM6A (lysine-specific demethylase 6A) and EHMT1 (euchromatic histone-lysine N-methyltransferase 1) have also been associated with syndromic congenital heart disease due to defects in NCC development." (PMID 35108221, 2022).